HOXA9 (homeobox A9)
Diseases named in the same sentence as HOXA9 in open-access papers (continued):
Sharing a sentence is not in itself a finding about the gene and the disease.
acute myeloid leukemia (continued). "Notably, HOXA9 is over-expressed up to 13-fold in >50% of acute myeloid leukemia (AML) cases, and its increased expression is associated with poor prognosis." (PMID 31120998, 2019). "For example, an MLL-AF10 fusion promotes DOT1L-mediated methylation of H3K79 at the HoxA9 promoter, which contributes to upregulation of expression of HoxA9 in acute myeloid leukemia." (PMID 29495487, 2018). "High expressions of HOXA7, HOXA9, and HOXA10 are frequently seen in acute myeloid leukaemia (AML) and the overexpression of HOXA9 is linked to a poor prognosis." (PMID 28515451, 2017). "Syk inhibition disrupts the regulatory loop and prolongs survival of mice with Hoxa9/Meis1-driven acute myeloid leukemia." (PMID 28399410, 2017). "This is exemplified by the observation that whereas mutational loss of EZH2 promotes the development of myelodysplastic syndrome (MDS), it attenuates MDS progression to acute myeloid leukemia by suppressing expression of the leukemic oncogene Hoxa9." (PMID 28758948, 2017). "HOXA9 is part of the A cluster on chromosome 7, and has been shown to act as an oncogene in acute myeloid leukemia, whereas silencing of HOXA9 by promoter methylation has been detected in several solid tumors such as breast, lung, ovarian and oral cancer." (PMID 27598218, 2016). "The PBX3 protein was also found to be a critical cofactor of HOXA9 in leukemogenesis, and targeting of the interaction between the two proteins was deemed to be a feasible strategy to treat acute myeloid leukemia with PBX3 gene overexpression." (PMID 25875009, 2015). "This is the first description of a molecular link between HoxA9 and the regulation of Bcl-2 family members in acute myeloid leukemia." (PMID 24177192, 2013). "The "TAKEDA_NUP9_HOXA9_3D_UP" gene set includes genes upregulated by the fusion protein NUP98-HOXA9, which occurs in acute myeloid leukemia." (PMID 21619705, 2011). "Meis1 and Hoxa9 are targets of translocation in human pre-B leukaemia and acute myeloid leukaemia (AML), respectively, and they are frequently co-expressed in human AML." (PMID 19285540, 2009). "Additionally, in acute myeloid leukemia (AML), WBP5 overexpression has been associated with poor prognosis, correlating with increased expression of HOX gene cluster (HOXA5, HOXA7, HOXA9, and HOXA10), MEIS1, and FOXC1." (PMID 40002180, 2025). "Indeed, co-expression of MEIS1 with HoxA9 can induce growth factor-dependent oligoclonal acute myeloid leukemia in less than three months in mice." (PMID 34698191, 2021). "Hoxa9 is critical for the development and self-renewal of healthy HSCs, but its ectopic co-expression with Meis1 in haematopoietic stem and progenitor cells leads to rapid acute myeloid leukaemia (AML) onset in mice." (PMID 33674652, 2021). "This is particularly the case of HOXA9 in acute myeloid leukemia (AML)." (PMID 31213012, 2019). "For example, HOXA9 has been established as a driver of proliferation in acute myeloid leukemia (AML) and its therapeutic value in this disease has been explored in a number of studies." (PMID 38989007, 2024). "HOXA9, a member of HOX family belonging to the HOXA cluster, is often studied in acute myeloid leukemia (AML), which is linked to proliferation, differentiation, and progenitor self-renewal maintenance." (PMID 36376832, 2022). "Indeed, MEIS1 forms complexes with HOXA9 in acute myeloid leukemia to drive carcinogenesis." (PMID 35743243, 2022). "In acute myeloid leukemia (AML), G9a inhibition attenuates the transcriptional activity of the leukemogenic transcription factor HoxA9 and thus promotes AML proliferation, progression, and self-renewal." (PMID 34685453, 2021). "For example, in acute myeloid leukemia (AML), MSI2 expression has been shown to be an adverse prognostic marker that maintains the self-renewal program in AML by interacting with HOXA9, MYC, and IKZF2 mRNAs." (PMID 32448269, 2020).
acute myeloid leukemia (continued). "A poor prognosis subtype of acute myeloid leukemia (AML) is characterized by increased expression of a set of homeodomain (HD) transcription factors, including HoxA9, HoxA10 and Cdx4." (PMID 27340869, 2016). "Indeed, BCL2 was recently shown to be a target of HOXA9 in acute myeloid leukemia." (PMID 25762636, 2015). "Moreover, HoxA9 has been found to be a key regulator that induces acute myeloid leukemia in mice." (PMID 19825192, 2009). "NUP98-HOXA9 is an oncogenic fusion protein associated with acute myeloid leukemia (AML) that consists of an N-terminal, FG repeat-rich portion of the nucleoporin NUP98 fused to the homeodomain region of HOXA9." (PMID 19696924, 2009). "Researchers have examined the role of HOX genes (HOXA9 and HOXB3) and MEIS1 in the pathogenesis of acute myeloid leukemia (AML) in murine models." (PMID 41226583, 2025). "Additionally, DHODH inhibition has shown to overcome differentiation arrest in HOXA9-expressing acute myeloid leukemia (AML) in both in vitro and mouse models of AML." (PMID 40961924, 2025). "In acute myeloid leukemia (AML), NAT10 knockout blocks the translational efficiency of target genes such as SLC1 A4 and HOXA9/MENIN, disrupts serine metabolic reprogramming, impairs leukemia stem cell self-renewal, and enhances chemotherapeutic sensitivity." (PMID 40588654, 2025). "This includes acute myeloid leukemia (AML) where HOTTIP facilitates leukemogenesis through R-loop creation and HOXA9 regulation." (PMID 40616679, 2025). "The homeobox A9 (HOXA9), a member of the HOXA family, has been extensively investigated, mainly in acute myeloid leukemia (AML)." (PMID 38285101, 2024). "Interestingly, the upstream region of human NUP96 is the NUP98 coding region, and NUP98 chromosomal translocation (fusion with the Homeobox A9 (HOXA9) gene) has been observed in patients with acute myeloid leukemia (AML)." (PMID 39080077, 2024). "For example, the fusion oncoprotein NUP98-HOXA9 (the IDRs (FG repeat) of NUP98 and the DNA-binding structural domain of HOXA9) drives abnormal remote chromatin interactions via LLPS, leading to acute myeloid leukemia." (PMID 39253293, 2024). "Here, using HOXA9-reporter-based genome-wide CRISPR/Cas9 screens, we identified that RBM5 is a positive regulator for maintaining HOXA9 expression and acute myeloid leukemia survival." (PMID 38216972, 2024). "The inhibitors suppressed expression of MLL target genes HoxA9, Meis1 and Myc, and selectively inhibited proliferation of MLL-r and other acute myeloid leukemia cells with EC50 values as low as 4.7 μM." (PMID 37958457, 2023). "HOXA9 plays an important role in acute myeloid leukaemia (AML) prognosis by promoting blood cell expansion and altering differentiation; however, the function of HOXA9 in other blood malignancies is still unclear." (PMID 36192425, 2022). "For instance, TET1 has been considered as a critical oncogenic epigenetic regulator in acute myeloid leukemia (AML), which plays its role by promoting the expression of oncogenic targets, including HOXA9, MEIS1 and PBX3, and suppressing the expression of tumor suppressor miR-22." (PMID 34957093, 2021). "UBE2E1 links with HOX gene regulation for its prognostic role in acute myeloid leukemia because HOX gene (HOXA9 and HOXA10) promotes acute myeloid leukemia leukemogenesis." (PMID 34769401, 2021). "SETDB1 functions as a tumor suppressor in Acute Myeloid Leukemia (AML) by promoter histone methylation and repression of tumorigenic genes, such as Sineoculis homeobox homolog 1 (Six1), HoxA9 and Dedicator of Cytokinesis 1 (Dock1)." (PMID 34440561, 2021). "HOXA9 and MEIS1 are frequently upregulated in acute myeloid leukemia (AML), including those with MLL-rearrangement." (PMID 34502319, 2021). "Concomitantly elevated expression levels of HOXA9 and HOXA10 together with ID2 in cell lines containing MLL translocations confirmed this form of regulation in both ALL and acute myeloid leukemia." (PMID 20565746, 2010).
acute myeloid leukemia (continued). "In particular, the HOXA9 and HOXA10 homeobox genes are frequently over-expressed in acute myeloid leukemias (AMLs)." (PMID 20846384, 2010). "In addition to promoter CpG methylation, HOXA9 is regulated by miRNAs in NSCLC, acute myeloid leukemia (AML), osteosarcoma, epithelial ovarian cancer, CRC, glioma, and uveal melanoma." (PMID 38904676, 2024). "Xinyue Zhou and Rui Lu discovered that SCUBE1 involving in the initiation and maintenance of MLL-rearranged (MLL-r) acute myeloid leukemia is a novel transcriptional target of HOXA9 and MEIS1, understanding the role of SCUBE1 is contributed to clarify the mechanism of HOXA9/MEIS1in human diseases." (PMID 36376832, 2022). "Similarly, Tribbles homolog 2 functions as an oncogene in inducing murine acute myelogenous leukemia (AML) and cooperates with HoxA9 to accelerate the onset of AML in vivo, which is consistent with the fact that Trib2 is highly expressed in a particular subset of human AML patients." (PMID 30266989, 2019). "One study showed that PBX3 is a potential pathologic cofactor of HOXA9 involved in cytogenetically abnormal acute myeloid leukemia (CA-AML), particularly MLL-rearranged AML." (PMID 30154863, 2018). "Acute myeloid leukemia (AML) with mixed lineage leukemia 1 (MLL1) gene rearrangement is characterized by increased expression of a set of homeodomain transcription factors, including homeobox A9 (HOXA9) and HOXA10." (PMID 32467231, 2020). "In acute myeloid leukemia (AML) patients, the Methyltransferase 1/WD repeat domain 4 (METTL1/WDR4) complex catalyzes m7G modification of tRNA, enhancing translation efficiency of specific mRNAs (e.g., HOXA9, MEIS1) to maintain AML cell proliferation and stemness." (PMID 41550494, 2026). "However, HoxA9 selective collaboration with Meis1, but not with Prep1, drastically lowers the latency of acute myeloid leukemia (AML) onset in mice." (PMID 24809472, 2014). "Indeed, the presence of MLL rearrangements in both acute lymphoblastic leukemia (ALL) and acute myeloid leukemia (AML) seems to relate with high level expression of genes normally expressed in HSCs during the early stages of hematopoiesis, such as FLT3 and HOXA9." (PMID 23977280, 2013).
ovarian carcinoma (44 papers, 2007 to 2026). A malignant neoplasm originating from the surface ovarian epithelium. "In ovarian cancer, significant associations between HOXA9 and presence of ascites and residual disease were detected." (PMID 39462379, 2024). "Lower expression of HOXA9, accompanied by hypermethylation of its promoter region, was diagnostic or prognostic biomarker in tumors such as non-small cell lung cancer, ovarian cancer, and head and neck squamous cell carcinoma." (PMID 36387262, 2022). "In ovarian cancer, high HOXA9 expression was associated with elevated M2 macrophages." (PMID 39462379, 2024). "Although, the methylation analyses of Hoxa9 with large cohorts has shown that Hoxa9 is hypermethylated in both high-grade serous ovarian cancer and primary ovarian cancer patients, the association of hypermethylation with the stage, histological types, grade, and ascites could not be established." (PMID 33402862, 2020). "Similar accuracy in the detection of early ovarian cancer has been achieved by the evaluation of HOXA9 methylation." (PMID 41301911, 2025). "In ovarian cancer, HOXA9 expression induces normal peritoneal fibroblasts to adopt a cancer-associated fibroblast (CAF) phenotype, stimulating the growth of ovarian cancer and endothelial cells." (PMID 38285101, 2024). "Consistent with previous reports, HOXA9 (cg16104915) was hypermethylated in cutaneous melanoma, lung, bladder, breast, and ovarian cancer." (PMID 38336771, 2024). "Recent studies have found that the abnormal expression of the HOXA9 gene is closely related to acute leukemia, glioblastoma, ovarian cancer, lung cancer, breast cancer, and other tumors." (PMID 35111226, 2022). "The homeobox A9 (HOXA9) expression in ovarian cancer cells stimulated chemotaxis of peritoneal macrophages and induced macrophages to acquire M2-like features." (PMID 36035994, 2022). "Methylated Homeobox A9 circulating tumor DNA (meth-HOXA9) has been suggested as a blood-based biomarker in epithelial ovarian cancer (EOC), although its prognostic significance remains unproven." (PMID 35406538, 2022). "HOXA9 promoter methylation was found in ovarian cancer revealed that the potential of HOXA9 methylation is a good diagnostic biomarker used in early screening of ovarian cancer." (PMID 36376832, 2022). "Methylation pattern was analyzed in ovarian cancer tissue samples through clonal sodium bisulfite DNA sequencing in the promoter region harboring a total of 19, 14, and 26 CpG sites for HOXA9, HIC1, and SOX1 gene, respectively." (PMID 34778370, 2021). "The combined panel of HOXA9 + HIC1 showed the best discriminatory efficiencies at all stages of ovarian cancer (80.0% (16/20) of stage I/II, 90.7% (49/54) of stage III, and 90.9% (10/11) of stage IV of ovarian cancer)." (PMID 34778370, 2021). "A prior study showed that the combined detection of HIC1 with another tumor suppressor gene, HOXA9, possessed great potential for the recognition of ovarian cancer." (PMID 35071242, 2021). "Previous studies showed that BMPER, CXCL10, and HOXA9 promote tumor angiogenesis and tumorigenesis in lung cancer, colon cancer, basal cell carcinoma, ovarian cancer, and liver tumor." (PMID 32432046, 2020). "Tumor-specific methylation analysis of HoxA9 in patients with ovarian cancer in phase II clinical trials with bevacizumab and tocotrienol chemotherapy revealed that HoxA9 methylation was increased after 1 cycle of chemotherapy." (PMID 33402862, 2020). "It has been stated that Rsk4, Sparc, and Hoxa9 function as oncogenes in ovarian cancer development, since they have less promotor methylation correlated with a high-grade tumor." (PMID 33402862, 2020). "In recent human studies, up-expression of HOXA9 can stimulate the progression of ovarian cancer by promoting an immunosuppressive microenvironment through paracrine effects in peritoneal macrophages." (PMID 31083386, 2019).
ovarian carcinoma (continued). "Similar reports of the action of HOXA9 have shown that HOXA9 suppression via microRNA-196b (which is overexpressed in recurrent compared to primary epithelial ovarian cancer) increased the invasiveness of SKOV-3 cells in vitro." (PMID 31382546, 2019). "CAFs secretes key pro-angiogenic factor VEGF-A as a result of HOXA9 upregulation from ovarian cancer cells, promoting proliferation and invasiveness of endothelial cells so as to trigger angiogenesis." (PMID 31888563, 2019). "In ovarian cancer, HOXA9 transcriptionally activates TGF-β2 to stimulate the proliferation of fibroblasts for the formation of a suitable microenvironment and promotes cancer progression." (PMID 29662084, 2018). "On the other hand, HOXA9 promotes homotypic and heterotypic cell interactions that facilitate ovarian cancer dissemination via its induction of P-cadherin." (PMID 28969042, 2017). "On the contrary, HOXA9 was believed to simulate ovarian cancer progression by inducing peritoneal macrophages to acquire an M2 tumour‐promoting phenotype 54." (PMID 28780773, 2017). "asserted that the HOXA9 expression in epithelial ovarian cancer cells promised a comfortable environment for tumour growth." (PMID 28780773, 2017). "There is clear evidence for this in ovarian cancer where the expression of HOXA9, HOXA10 or HOXA11 confer a serous, endometrioid-like and mucinous-like phenotype respectively." (PMID 20219106, 2010). "A previous study has suggested that the development of various histotypes of ovarian cancer in mice is partly dependent on the ectopic expression levels of HOXA9, however, additional studies are needed before this can be concluded." (PMID 17623056, 2007). "CpG island promoter hypermethylation of tumour suppressor genes is a common event in primary ovarian carcinomas and cell lines, and HOXA9, HOXB5, SCGB3A1, and CRABP1, represent novel hypermethylated target genes in this disease." (PMID 17623056, 2007). "In the present study, the promoter of HOXA9 was frequently hypermethylated and associated with early-stage (FIGO stage I-II) ovarian carcinomas." (PMID 17623056, 2007). "Additionally, research also focused on the role of HOXA9 in solid tumors such as ovarian cancer, and breast cancer." (PMID 36376832, 2022). "Our WGBS analysis also identified some differentially methylated genes that have been identified in HGSOCs in other studies, notably HOXA9 which was found to be methylated in up to 95% of ovarian cancers in a study of 80 primary tumors from Montavon and colleagues." (PMID 35883104, 2022). "Moreover, higher sensitivity in identifying early stages of ovarian cancer was exhibited by HOXA9, HIC1, and SOX1, which further confirms their utility as a potential biomarker for early-stage detection of EOC." (PMID 34778370, 2021). "Interestingly, a study on ovarian cancer cell line and normal tissue showed that DNA methylation of some of the analyzed genes, including Hoxa9, Hoxa10, MiR-34b, Prom1, Cables1, Sparc, and Rsk4, had an inverse correlation with their expression level." (PMID 33402862, 2020). "On the other hand, a series of studies on ovarian cancer cells indicated that adaptation to the peritoneal environment and guidance of different types of stromal cells to reinforce tumor growth were stimulated by Hoxa9." (PMID 33402862, 2020). "This suggested that Hoxa9 could be a possible biomarker for early response to inefficient chemotherapy in ovarian cancer patients." (PMID 33402862, 2020). "Likewise, HOXA9 encourages epithelial ovarian cancer growth in mouse xenograft models and supports the generation of a microenvironment for tumour growth." (PMID 31043660, 2019). "However, DACH1 is up-regulated in myeloid leukemia via interaction with HOXA9 and overexpression in ovarian cancer with poor prognosis as promotion sensitivity gene." (PMID 30261897, 2018). "Hsa-miR-196b promotes invasiveness of ovarian cancer cells through regulation of homeobox A9." (PMID 29755664, 2018).